RIMS4 (regulating synaptic membrane exocytosis 4)
Description:
Regulates synaptic membrane exocytosis.
Synonyms: RIM 4; C20orf190; dJ781B1.3; RIM-4; RIM4; RIM4-gamma; RIM4gamma
Tractability: PROTAC: ubiquitination databases record sites on it; its protein half-life has been measured.
Gene: Protein-coding gene on chromosome 20 (44,751,808 to 44,810,546, reverse strand). Ensembl gene ENSG00000101098.
Subcellular location: Synapse
Subcellular location (Human Protein Atlas): Nucleoplasm
Gene Ontology:
Molecular function: protein binding; transmembrane transporter binding; small GTPase binding
Biological process: regulation of membrane potential; regulation of synaptic vesicle exocytosis; exocytosis
Cellular component: presynaptic active zone; synaptic membrane; membrane; synapse
Genetic constraint (gnomAD): Loss-of-function variants: 7 observed, 27.33 expected, observed/expected ratio (o/e) 0.26, 90% interval 0.14 to 0.48. The upper end of that interval is the gene's LOEUF score, 0.48, which puts it in group 2 of 6, group 1 being the genes least tolerant of losing a copy. Missense variants: 174 observed, 348.99 expected, observed/expected ratio (o/e) 0.5, 90% interval 0.44 to 0.56. Synonymous variants: 126 observed, 149.79 expected, observed/expected ratio (o/e) 0.84, 90% interval 0.73 to 0.98.
Homologues: Orthologues: chimpanzee RIMS4 (100% identical), macaque RIMS4 (99% identical), dog RIMS4 (99% identical), mouse Rims4 (99% identical), pig RIMS4 (99% identical), rat Rims4 (99% identical), guinea pig RIMS4 (92% identical), tropical clawed frog rims4 (87% identical), zebrafish rims4 (84% identical), rabbit RIMS4 (79% identical), Drosophila melanogaster Rim (39% identical), Caenorhabditis elegans unc-10 (37% identical). Paralogues in human: RIMS1 (64% identical), RIMS2 (63% identical), RIMS3 (54% identical), NANOGNB (10% identical).
Diseases named in the same sentence as RIMS4 in open-access papers:
RIMS4 is named in the same sentence as 8 diseases in open-access papers, as found by Europe PMC text mining. Sharing a sentence is not in itself a finding about the gene and the disease. The quoted sentences say what the papers report.
autism (6 papers, 2018 to 2025). Persistent deficits in social interaction and communication and interaction as well as a markedly restricted repertoire of activity and interest as well as repetitive patterns of behavior. "No study so far has reported the association of RIMS2 with genetic disorders, but its homologues RIMS3 and RIMS4 were implicated autism risk factors." (PMID 30619482, 2018). "We can therefore hypothesize that the de novo RIMS4 truncating stop variant perturbs the fine-tuning of glutamatergic release at the synapse and contributes to autism." (PMID 30675382, 2019).
breast carcinoma (1 paper, 2021). "In addition, the BC_gBRCA2 group showed overexpression of RIMS4 indicative of estrogen-positive cancers as well as CNTFR, which is shown to be deregulated in breast cancer, however, with unknown clinical impact." (PMID 33525353, 2021).
RIMS4 also shares sentences with these, for which no sentence is quoted: Intellectual disability (2 papers); cancer (1); epilepsy (1); genetic disorders (1); schizophrenia (1); tumor (1).